ZNF33BP1 (zinc finger protein 33B pseudogene 1)
Gene: Processed pseudogene on chromosome 10 (37,794,276 to 37,796,109, reverse strand). Ensembl gene ENSG00000225192.
Diseases named in the same sentence as ZNF33BP1 in open-access papers:
ZNF33BP1 is named in the same sentence as 1 disease in open-access papers, as found by Europe PMC text mining. Sharing a sentence is not in itself a finding about the gene and the disease.
ZNF33BP1 shares sentences with these, for which no sentence is quoted: genetic diseases (1 paper).